CD4 (CD4 molecule)
Diseases named in the same sentence as CD4 in open-access papers (continued):
Sharing a sentence is not in itself a finding about the gene and the disease.
tumor (continued). "When we look at the tumor types in our study, when the control-study group is compared, inflammation is only in the adenocarcinoma subtype; intratumoral CD4/CD8 ratio was observed to be statistically significant only in the SCC tumor subtype." (PMID 38468248, 2024). "CLEVER-1 promotes CD4+ FoxP3+ Tregs transmigration through ICAM-1 and vascular-associated protein-1 (VAP-1) and further infiltration within the tumor niche." (PMID 39596815, 2024). "The influence of CBL0137 HAI on immune cell subsets was not limited to MDSCs and CD8+ T cells but also skewed CD4+ T cell compartments towards a favorable anti-tumor phenotype." (PMID 39518148, 2024). "Meanwhile, high PD-L1+ lymphocyte infiltration in islets was predominantly found in tumours with high levels of IL-17A+CD4+ T cells in islets and Foxp3+CD4+ T cells in islets and stroma (p = 0.032, p = 0.009 and p = 0.034, respectively)." (PMID 39409156, 2024). "The increase in CD4 + T-cells highlights their important role in mediating antitumor immunity, in contrast to the direct tumor-killing effects of CD8 + T-cells." (PMID 39316338, 2024). "The volcano plots showed interactions between tumor cells and CD4 T cells as well as DCs with B cells in PR while interactions between CD8 and Tregs as well as B cells and macrophages were seen in PD." (PMID 39606482, 2024). "In a single-cell study of T-cell phenotypes in supercentenarians linking high fractions of CD4+ cytotoxic T-cells to repeated viral exposure and favourable anti-tumor immunity, extracted CD4+ cytotoxic T-cells secreted TNF-α and IFN-γ upon ex vivo stimulation." (PMID 38049509, 2024). "Studies on NSCLC have revealed that tumour-infiltrating B cells present antigens and activate CD4 + T cells in certain NSCLC patients." (PMID 38582847, 2024). "Using this system, we observed that prophylactic immunization with necroptotic cells was sufficient to drive protective anti-tumor CD4+ T cell responses." (PMID 38858387, 2024). "Resembling human AITL disease, mAITL CD4+ tumor cells are indeed positive for Tfh markers (PD-1, CXCR5)." (PMID 38897995, 2024). "Tumours with positive PD-L1 TPS, IC, or CPS expression were more likely to have low IL-17A+CD4+ T cell infiltration in the tumour stroma." (PMID 39409156, 2024). "Increasing evidence demonstrates that a high density of CD8+ and CD4+ T lymphocytes in tumours is an independent predictor for a worse prognosis." (PMID 38962454, 2024). "The increase in CD8+ GrzB+ T cells, CD8+ IFNγ+ T cells and CD4+ IFNγ+ T cells under combination therapy indicated activation of T cell-mediated tumor toxicity." (PMID 38589867, 2024). "Spleens from the chitin-treated 66cl4 tumor-bearing mice showed a significant increase in CD4+ T-cell percentages compared to spleens from untreated and anti-PD-1-treated 66cl4 tumor-bearing mice." (PMID 38605414, 2024). "The tumor microenvironment comprises a heterogeneous population of anti-tumor immune cells (e.g., CD8+ T cells and CD4+ T cells) and pro-tumor suppressive cells (e.g., Tregs, CAFs, and MDSCs)." (PMID 39596296, 2024). "In contrast, CD4+ T cells were of little importance to the anti-tumor activity of circAtxn7 ablation." (PMID 38216551, 2024). "The collective evidence conclusively underscores that the therapeutic synergy achieved through combination therapy effectively fosters the infiltration of T cells, primarily CD4 + and activated CD4 + T cells, into the tumor microenvironment." (PMID 38504270, 2024). "Temozolomide decreased tumour growth and improved median survival but increased the infiltration of CD4+ Tregs." (PMID 39048947, 2024). "Previously, we revealed that cryo-thermal therapy elicited CD4+ Th1-dominant differentiation at the late stage in the B16F10 tumor model, thereby leading to long-term survival." (PMID 38827732, 2024). "We established CD8+ T cells as the center cells and calculated the distance to the nearest tumor cells (left) and CD4+ T cells (right)." (PMID 38611111, 2024).
tumor (continued). "Along with CD8+ T cells,there are tumor-specific CD4+ T helper (Th) cells that can recognizetumor antigens and effectively slow tumor growth in animal models in theabsence of CTLs." (PMID 39555171, 2024). "These TIM-3(+) CD4 T cells in tumor tissues produce lower levels of Th1 cytokines and express higher levels of CD25, Foxp3, CTLA-4, and GITR." (PMID 39206199, 2024). "These therapeutic effects were associated with increased CD4+ and CD8+ T cells, and IFN-γ and TNF-α in tumor tissues, indicating that CMFn@OXA NPs induced a strong anti-tumor immune response." (PMID 39339217, 2024). "The results revealed a significant reduction in various anti-tumor immune cells, including CD4+ central memory T cells, dendritic cells, mast cells, natural killer T cells, and monocytes, in the high-risk group, whereas T helper 2 (Th2) cells were increased." (PMID 38293522, 2024). "To explore the contribution of T cells to the anti-tumor effect of zebularine, we used monoclonal antibodies (mAb) to target CD4+ or CD8+ T cells in zebularine-treated tumor-bearing immunocompetent C57BL/6 mice." (PMID 38755254, 2024). "Further analysis of infiltrated immune cells in tumor tissues showed that CD4 memory, CD8 effector, CD8 naive, B cells, NK cells and DC cells were more abundant in the tCAF score high group than the tCAF score low group." (PMID 38580966, 2024). "There is cross-reactivity between human tumor antigens and bacterial antigens due to molecular mimicry, allowing tumor antigen recognition by CD4+ T cells and CD8+ cytotoxic T cells." (PMID 38994360, 2024). "Apatinib at low doses significantly alleviated tumor hypoxia, increased CD4+ and CD8+ cell infiltration, and decreased TGF-β levels at certain time points, suggesting that angiogenesis inhibitors have a true immunomodulatory effect." (PMID 38532022, 2024). "Apart from the established cytotoxic capacity of CD8+T cells, CD4+ T cells emerge as a multifaceted player in anti-tumor immunity." (PMID 39105803, 2024). "Target cells are recognized via the interaction of the Tag7 CD4+-T lymphocyte with the main heat shock protein Hsp70 on the surface of tumor cells." (PMID 38203798, 2024). "The CD4:CD8 ratio was 2.72 (median) in naïve tumor tissue but fell to 0.26 following anti-PD1 combination therapy." (PMID 39334513, 2024). "A combination regimen with GPs and an αPD-1 mAb was found to improve the ratio of CD8+/CD4+ T cells and downregulate FoxP3 Treg cells in both tumor and peripheral tissues." (PMID 39567970, 2024). "CD4+ cells, which had infiltrated into the tumor following anti-CTLA-4 Ab administration, showed a significant decrease in infiltration ability when combined with the IFN-g neutralizing Ab." (PMID 39106430, 2024). "In contrast to the CD8+ cytotoxic T cells which are the most powerful effectors in the anticancer immune response, the exact mechanism of how CD4+ T cells are involved in the anti-tumour immunity is less clear." (PMID 38816839, 2024). "Lastly, using a syngeneic murine model, SGLT2 inhibitors in concert with 2’3’-cGAMP constrained osteosarcoma tumour growth and potentiated CD45+ CD4+/CD45+ CD8+ T-lymphocyte infiltration at tumour sites." (PMID 39403376, 2024). "Over the next few years, Gaberet al. investigated the interaction between the roles of macrophage migration inhibitors (MIF), HIF, and GCs in human primary non-tumor CD4 + Th cells and Jurkat T cells." (PMID 38671500, 2024). "As reported, CXCL10 can recruit both immunoactive cells such as CD8+T cells and CD4+T cells, and immuosuprresive cells like MDSCs into the tumor microenvironment." (PMID 38951890, 2024). "Several studies have shown that upregulation of ts-MHC-II, which is typically associated with increased numbers of CD4+ and CD8+ tumor-infiltrating lymphocytes, leads to tumor rejection and improves the immunotherapy response." (PMID 38931345, 2024).
tumor (continued). "To this end, we categorized tumors as CD4high or CD4low (=<median of % CD4+ T cells in tumor) and fit logistic regression models to predict T cell infiltration by the CD4+ T cell clusters (in PBMCs) that we had identified by unsupervised CyTOF analysis." (PMID 38653982, 2024). "Our research indicates that TILs, particularly CD8+, CD3+ and CD4+ TILs, are associated with improved prognosis in NSCLC, supporting the notion that these immune cells contribute to anti-tumor immunity." (PMID 39372398, 2024). "While the EPIC analysis highlighted the predominance of CD4+ T cells in the tumor microenvironment, contrasting findings were observed when analyzing data from other platforms, where CD8+ T cells also showed significant infiltration patterns." (PMID 38668876, 2024). "Positive PD-L1 IC was more often seen in patients with high CD4+ T cells infiltration level in tumour tissue (p = 0.02)." (PMID 38541208, 2024). "The largest population of immune cells was tumor-associated macrophages (70.5%) that co-expressed CD14, CD4, CD11c, CD64, and HLA-DR." (PMID 39682129, 2024). "The presence of higher numbers of immune cell types, such as CD8 T cells, CD4 T cells, and natural killer cells, can enhance the body’s ability to recognize and destroy cancer cells, potentially leading to improved anti-tumor activity." (PMID 39408773, 2024). "Rag1−/− mice challenged with Id2fl/flCd4-Cre+ CD8+ T cells plus Id2fl/flCd4-Cre− CD4+ T cells had significantly decreased frequencies of adoptive tumor-infiltrating CD8+ T cells and CD4+ T cells." (PMID 38287103, 2024). "Eventually, tumor-specific CD4+ and CD8+ lymphocytes localize at the site of the lesion, leading to the destruction of tumor cells expressing the relevant antigens that still persist at the site." (PMID 39861800, 2024). "The hydrogen therapy by Mg‐CaCO3 can not only directly kill tumor cells, but also inhibit pro‐tumor and immune suppressive factors in CAFs, and thus augment immune activities of CD4+ T cells." (PMID 38757665, 2024). "Topical saquinavir, in the setting of CD4 T cell depletion and carcinogen exposure, can increase tumor-free survival and overall survival and decrease tumor growth rates." (PMID 39339897, 2024). "The granzyme B and perforin double positive CD4 + T cells were increased only in PAK1&4 double KO tumour." (PMID 38797819, 2024). "Compared to adjacent tissues, immunosuppressive CD4+ T-cell subpopulations, including Treg were more enriched in tumor tissue." (PMID 38649887, 2024). "The laser-assisted intradermal delivery of a tumor-specific tumor antigen combined with XCL1 resulted in the enhanced priming of CD8+ and CD4+ effector T cells by dermal DCs and better tumor control in a melanoma mouse model." (PMID 38928238, 2024). "cDC2s prime CD4+ T cell-mediated anti-tumour immunity when released from suppression by tumour regulatory T cells and stimulation with type 1 interferons promotes cDC1-like cross-presentation to CD8+ T cells from cDC2s." (PMID 38223410, 2024). "Once tumor antigens are endocytosed by resident dendritic cells (DCs) in tissues, DCs migrate to lymph nodes where they present processed peptide fragments to CD4+ helper T cells and CD8+ CTLs [1072,1073,1074,1075]." (PMID 39273409, 2024). "An additional indication that pDCs also serve an antigen-presenting function in CRC is their localization within the tertiary lymphatic structure of the tumor, directly adjacent to CD4+ T cells." (PMID 38927922, 2024). "Significantly, responders exhibited an elevated abundance of TLS and a greater presence of tumor-specific CD4+ and CD8+ T cells." (PMID 39763684, 2024). "Huh7 culture supernatants appear to promote CD4+CD25+ T-cell proliferation, suggesting that tumor-related factors play a key role in CD4+CD25+ cell expansion and suppressor ability." (PMID 39061246, 2024). "The frequencies of regulatory T cells (Treg) (CD4+ FoxP3+) and type 1 T helper (Th1) cells in tumor and TdLN were comparable between the genotypes." (PMID 38302493, 2024).
tumor (continued). "We used patient tumor slices to explore individual patient immune landscapes using multiplex immunofluorescence (IF) using a panel that detects CD4+ T cells, CD8+ T cells, regulatory T cells (Tregs), macrophages, and B cells." (PMID 38968363, 2024). "After 20 days of treatment, the percentage of central memory T cells (CD44+CD62L+) among the CD8+ T subset and the CD4+ T subset in the tumor from mice was significantly higher than that of the PBS group, with 17.4% and 31.6%, respectively." (PMID 38938647, 2024). "CD4+ T cells, also known as T helper lymphocytes, modulate immune responses through cytokine secretion, influencing inflammation and tumor growth as well as assisting in the activation of other immune cells." (PMID 39000195, 2024). "The IL-4, IL-10, and IL-13 cytokines released from CD4+Th2 immune cells have been shown to induce a phenotypic switch of naïve MΦ0 macrophages to the pro-tumor MΦ2 phenotype." (PMID 38397152, 2024). "In this regard, it has been reported that BCG therapy exerts pleiotropic effects, among which also the enhancement of the effector functions of tumor-specific CD4+ T cells." (PMID 38600583, 2024). "Collectively these results further highlight the role of CXCL9 and CXCL10 in potentiating, not only anti-tumor CD8+ T cells but also anti-tumor CD4+ T cells, including cytotoxic CD4+ T cells." (PMID 39474427, 2024). "Currently, tumor-infiltrating lymphocytes (TILs)—including subsets of helper CD4+ cells, B cells, NK cells, γδT cells, and myeloid cells—are considered crucial biomarkers in tumor immunotherapy." (PMID 38933280, 2024). "Consistent with other findings, Hes1-cKO slowed TC-1 tumor growth; however, depletion of CD4+ T cells completely abolished this effect." (PMID 39702544, 2024). "The stronger antitumor activity of IBI323 is associated with an increase in tumor-specific CD8+ and CD4+ T cells compared to each parental antibody in PD-L1/LAG-3 double-knocking mice carrying human PD-L1 knocking to MC38 tumors." (PMID 39252941, 2024). "To infer the interplay of each tumor cluster with immune cells, we quantified the communication probabilities between tumor clusters and CD4+ T cells, focusing on the MHC-II-mediated interactions, using CellChat." (PMID 39664386, 2024). "Tumor-infiltrating CD4+ T cells exert their function by undergoing differentiation into various subsets directed by functional polarization." (PMID 39703499, 2024). "Several studies have established that various cancers carry a large number of tumour‐infiltrating Treg cells, and the abundance of naïve CD4+ T cells and Tregs in cancer patients has been found to be closely associated with poor prognosis." (PMID 39601163, 2024). "Similar to the bone TIME, the liver appears to have distinct immune tolerance through multiple mechanisms including activation of Tregs and CD4- T cell death, affecting local and systemic tumour immunity." (PMID 38957472, 2024). "The frequency and absolute numbers of mItgb1-specific CD4+ tumour-infiltrating lymphocytes (TILs) from HDVax-treated or LDVax-treated mice were similar." (PMID 39048822, 2024). "By spatial context analysis, which measures proximities between CNs, we found that CNs within the CD4-rich CNC are the most segregated from those in the tumor-rich CNC." (PMID 38575670, 2024). "The critical role of CD4+ T cells in driving anti-tumour immunity has been widely recognized in recent years." (PMID 38475858, 2024). "We next characterized the phenotype of tumor-infiltrating CD4+ and CD8+ T cells using flow cytometry." (PMID 38429349, 2024). "Analysis of GPSM2 expression concerning tumor purity demonstrated highly positive correlation and correlations with the infiltration levels of CD4+ T cells and macrophages within CRC." (PMID 38674408, 2024).
tumor (continued). "In the context of GBM treatment using G47Δ, a third-generation oncolytic HSV-1 with triple mutations, a significant augmentation in CD4+ and CD8+ lymphocyte populations was observed as they rapidly infiltrated into tumor tissue." (PMID 39055561, 2024). "EPHA3 was reported related to tumor-specific antigens presented by HLA class II molecules to CD4+T cells." (PMID 38890738, 2024). "Upon recognition of tumor specific antigen presented by APCs, CD4 and CD8 naïve T cells undergo differentiation and become effector T cells." (PMID 38348038, 2024). "This influx of CD8+, CD4+ T lymphocytes and eosinophils suggested a robust enrichment of both innate and adaptive immune response against the tumor cells in the treated animals." (PMID 38524132, 2024). "The physical inability to make deeper contact with tumor surface antigens also imposes a kinetic inhibition in the ability of antigen-sensitized CD4 or CD8 cytotoxic T lymphocyte (CTL) cells to activate in response to shielded cognate antigens." (PMID 39165679, 2024). "Treg cells, a subset of CD4+ T cells, suppress immune responses and undermine anti-tumor T cell immunity." (PMID 39690159, 2024). "CD4+ T cells can engage tumor cells through various mechanisms, either by directly eliminating tumor cells via cytolysis or indirectly by modulating the tumor microenvironment." (PMID 38533503, 2024). "This study demonstrated a higher expression of RAMP1 for tumor-infiltrating immune cells (CD4+ T cells, cytotoxic CD8+ T cells, and NK cells) in OSCC patients compared to immune cells from the normal tissue of healthy individuals." (PMID 38334648, 2024). "Biopsy histology confirmed the presence of a larger number of tumor-infiltrating CD4+ and CD8+ T-cells and persistent low numbers of Foxp3+ cells following repeated G47∆ treatments." (PMID 38921005, 2024). "In mouse models of senescence driven by NrasG12V, senescence not only inhibits the proliferation of tumour cells, but also activates CD4+ T cells to eliminate tumour cells." (PMID 39270064, 2024). "In comparison to the high-risk group, the low-risk group exhibits significantly increased infiltration of B cells, CD8 T cells, activated CD4 T cells, follicular helper T cells (Tfh), regulatory T cells (Tregs), and resting mast cells in tumor tissues." (PMID 38365684, 2024). "In murine tumor models, ablation of Tregs results in activation of CD4+ or CD8+ Teff cells and rejection of solid tumors." (PMID 38995700, 2024). "In HSV vectors, encoding immunomodulatory cytokines like IL-2, IL-12, and GM-CSF enhances tumor regression mediated by CD4+ and CD8+ lymphocytes." (PMID 38731910, 2024). "Decreased IFN-γ and IL-2 levels were observed in tumor-infiltrating CD4+ T cells from the Id2fl/flCd4-Cre+ mice compared with the Id2fl/flCd4-Cre− mice, while no such differences were observed in CD8+ T cells." (PMID 38287103, 2024). "Here, across multiple tumor types, we identify IFNβ-expressing CD4+ T cells that have a Ki67+CXCL13+ and a partial PD-1+ phenotype." (PMID 38383773, 2024). "In cancer, cDC2s are often suppressed by regulatory T cells (Tregs), impairing trafficking to the lymph node and the presentation of tumor-derived antigens to CD4+ T cells." (PMID 39432076, 2024). "Tumor patients having the highest CD47 expression profile at baseline showed the greatest CD4+ and CD8+ T-cell influx post NACT and displayed a better prognosis." (PMID 39138571, 2024). "The ability of CD4+ TH17 cells to play pro-tumourigenic or anti-tumourigenic functions in tumour immunity and inflammation relies on the stimuli they encounter." (PMID 38339377, 2024). "In lung and cervical tumor samples, ERα signaling has been linked to decreased infiltration of CD4+ and CD8+ T cells into the tumor microenvironment." (PMID 39682229, 2024). "Similar to CD8+ T cells, CD4+ T cells secrete pro-inflammatory cytokines with direct anti-tumor effects." (PMID 38444857, 2024).